ALDH2 (aldehyde dehydrogenase 2 family member)
Diseases named in the same sentence as ALDH2 in open-access papers (continued):
Sharing a sentence is not in itself a finding about the gene and the disease.
cancer (continued). "However, there are no reports about the changes of ALDH2 and the research of cancer stem cells and immune-related research." (PMID 34670872, 2021). "Therefore, although XRCC1 mRNA levels alone have no prognostic value, low ALDH2 levels show a worse prognosis at 5 years, only in cancers showing a marked difference between ALDH2 and XRCC1 expression." (PMID 30088263, 2018). "Interestingly, we found that ALDH2 knockdown alone promotes higher survival rates for both the H1299 (column 3) and JHH4 (column 3) cells, supporting our observation that lower ALDH2 levels are advantageous for cancer cells." (PMID 30088263, 2018). "Importantly, we, for the first time, revealed that the protein expressions of ALDH2, CCNE1 and SMAD3 were significant and independent prognostic markers for patients with UTUC, which may facilitate the clinical management of this cancer." (PMID 25408144, 2014). "Construction of such a risk-factor-based appraisal model including the alcohol metabolizing genes ALDH2, ADH1B and behavioral factors of alcohol consumption and smoking could be useful for the evaluation and prediction of multiple metachronous SCC in UADT cancer patients in the future." (PMID 35330099, 2022). "A comprehensive assessment of the interplay between ALDH2‐rs671, ADH1B‐rs1229984 and alcohol consumption on risks of different cancer types in a large‐scale population‐based cohort study may provide valuable insights into the aetiological role of alcohol on different cancers." (PMID 35048370, 2022). "However, a comprehensive understanding of ALDH2 across human cancers is lacking." (PMID 35096916, 2021). "As ALDH2 is not found to be crucial during carcinogenesis, CVT‐10216 and ALDH423 have not yet been tested in cancer models." (PMID 36694633, 2023). "Notably, CNV had little impact on ALDH2 expression in most cancers, which also indicated CNV was not an important factor downregulating ALDH2 expression." (PMID 35096916, 2021). "Moreover our guess is supported by fully referenced literature, which shows the ALDH’s role in cancer stem cells, as a component of ALDH, ALDH2 should play the same role as ALDH does although it was not on clinical routine screening now." (PMID 29552329, 2018).
tumor (104 papers, 2012 to 2026). "Tumors derived from ALDH2-KO cells grew significantly faster than those from WT A375 cells, indicating that ALDH2 loss promotes tumor growth." (PMID 40558540, 2025). "Chronic EtOH administration has been reported to induce skin hyperpigmentation in Aldh2-deficient mice, suggesting a role for ALDH2 in skin biology and melanocyte physiology." (PMID 40558540, 2025). "Crucially, more comprehensive in vivo studies, including xenograft models with ALDH2-KO and rescue experiments with ALDH2-OE or enzyme activators, are warranted to further validate the causal role of ALDH2 in tumor progression and therapeutic response." (PMID 40558540, 2025). "TIMER revealed the association between aldehyde dehydrogenase 2 (ALDH2) and tumor immune microenvironment." (PMID 38378847, 2024). "Some processes and molecules involved in this evasion are being brought to light, molecules actually previously linked to tumor progression such as ALDH2 and which have now been linked to tumor evasion of the immune response." (PMID 39091493, 2024). "Taken together, our results found that low tumor ALDH2 levels were linked with copy-number alteration and hyper-methylation, as well as being negatively associated with T stage and predicting poor overall survival in the HPV-unrelated HNSC." (PMID 37476181, 2023). "This study also explored the potential mechanisms of ALDH2 by utilizing molecule interaction prediction, gene set enrichment, and genetic signature association analyses with tumor immune microenvironments." (PMID 37476181, 2023). "To evaluate the diagnostic efficacy of ALDH2, we performed ROC curve analysis on the expression data from tumour and normal tissues." (PMID 35169188, 2022). "In the present study, we explored ALDH2 expression in numerous neoplasms using The Cancer Genome Atlas (TCGA) and its association with HNSC patient prognosis." (PMID 35169188, 2022). "In this study, based on the imputed tumor response of 138 anticancer-drugs from a large cohort, we provided potential sensitive or resistant drug resources for ALDH2-deficient tumors." (PMID 35096916, 2021). "A low expression level of ALDH2 in CRC specimens was associated with a higher number of the tumor infiltrated CD3+ and CD8+ activated T cells." (PMID 34572930, 2021). "ALDH2 has tumor suppressive actions and polymorphisms in this gene is associated with increased risk to a number of alcohol-related cancers." (PMID 31974410, 2020). "Univariate analysis revealed that ALDH2 “GG” genotype, microvascular invasion, macrovascular invasion, higher tumor number, larger tumor size, AFP, and AST were significantly associated with a shorter time-to-distant metastasis." (PMID 31737110, 2019). "Univariate analysis revealed that ALDH2 “GG” genotype, presence of ascites on surgery, microvascular invasion, macrovascular invasion, higher tumor number, larger tumor size, albumin, and AST were significantly associated with shorter overall survival." (PMID 31737110, 2019). "Several genome- wide association (GWA) studies have demonstrated that the ALDH2 gene rs671 G>A polymorphism can significantly increase the risk of some tumours, including upper aerodigestive tract (UADT) cancer and oesophageal squamous cell carcinoma (OSCC)." (PMID 29254255, 2017). "As for the other three possible tumor subtypes, ALDH2 was associated with KIT exon 11 insertions (p = 0.03) and the null GSTT1 genotype was associated with PDGFRA-mutated tumors (p = 0.04)." (PMID 23637977, 2013). "The study linked this increased tumor load to a gradual downregulation of two metabolic genes, Acyl-CoA synthetase long chain family member 1 (Acsl1) and aldehyde dehydrogenase family member 2 (Aldh2) mediated through a specific miRNA, miR-27a-3p." (PMID 38681863, 2024).
tumor (continued). "Notably, ALDH2 dysfunction has been widely reported to be associated with tumorigenesis and tumor progression, which is often considered a feasible prognostic marker in different solid tumor types." (PMID 36694633, 2023). "ALDH2 was also found to be positively correlated with PD-L1 expression in tumor tissue, indicating that these immune cells have suppressive features." (PMID 41550766, 2026). "The results revealed that the expression of MAOA, AKR1A1, ALDH9A1, HAAO, and ALDH2 was significantly downregulated in ESCC tumor tissues compared to non-tumor tissues." (PMID 40821701, 2025). "CRISPR/Cas9-mediated ALDH2 knockout in ALDH2-normal A375 cells promoted tumor growth and MAPK/ERK activation." (PMID 40558540, 2025). "The accelerated tumor growth in ALDH2-KO A375 cells was, at least in part, attributed to elevated AcAH and ROS production." (PMID 40558540, 2025). "The results revealed that in the ALDH2-overexpression group, tumour cell proliferation was significantly increased, and the mice exhibited obvious resistance to Ara-C." (PMID 40796730, 2025). "ALDH2 was overexpressed in KG1a cells (KG1aALDH2), and a mouse subcutaneous tumour model was subsequently established." (PMID 40796730, 2025). "The ALDH2 rs671 genotype was significantly correlated with tumor recurrence (3 [11.5%] vs 16 [36.3%], P = .024) and serum albumin levels (4.1 ± 0.3, 4.3 ± 0.3, P = .029)." (PMID 40660548, 2025). "Inhibition of ALDH2 expression restored the ability of Ara-C to inhibit the growth of tumour cells, and the survival and health status of the mice were significantly improved." (PMID 40796730, 2025). "In conclusion, these results suggest that ALDH2 upregulation significantly increases resistance to Ara-C and promotes tumour proliferation, accompanied by increased mitochondrial content and higher expression levels of proteins encoded by mtDNA." (PMID 40796730, 2025). "To investigate the biological effects of ALDH2-KO, we evaluated A375 tumor growth by injecting nude mice with WT and ALDH2-KO A375 cells." (PMID 40558540, 2025). "The results of immunofluorescence staining of tumour tissue sections indicated that the mitochondrial fluorescence intensity increased significantly in the ALDH2-overexpression group, and the proportion of exhibiting fluorescence also tended to increase." (PMID 40796730, 2025). "ALDH2 expression was found to be reduced in tumor tissues, indicating its potential as a protective gene in HCC." (PMID 39132147, 2024). "Mechanistic experiments identified ALDH2 as a key HCC tumor suppressor, finding its overexpression attenuated Treg by suppressing the β-catenin and TGF-β1 signaling." (PMID 38725845, 2024). "Single-cell transcriptomics revealed selective ALDH2 expression within the tumor cell compartment, which was downregulated in 30 pairs of HCC tissues compared to paired non-tumor tissues at mRNA and protein levels." (PMID 38725845, 2024). "The results showed that IL2RA, DNMT3B, ADRM1, and NRIP1 were highly expressed in tumor tissue compared to normal tissue, while ALDH2, NYNRIN, LSP1, and CALCRL were the opposite." (PMID 38322112, 2024). "In contrast, our findings indicate that ALDH2 exerts a tumour suppressive effect, as evidenced by its downregulation in MM patients and overexpression‐induced inhibition of MM cells." (PMID 39245797, 2024). "We identified ALDH2 as a tumor suppressor in HCC, with three novel phosphorylation sites mediated by protein kinase C zeta that enhanced enzymatic activity." (PMID 38725845, 2024). "Low expression of ALDH2 had a significant impact on the infiltrating levels of immune cells, promoting immune infiltration in tumor microenvironment." (PMID 38378847, 2024).
tumor (continued). "This was mediated via higher selective accumulation of DC(I + II) NPs in only tumor tissues and oxidant activity, causing stronger selective inhibition of mitochondrial enzymes (PDH, SDH, and ALDH2) than DC(I)NPs." (PMID 39076585, 2024). "These tumor suppressive functions of ALDH2 are consistent with the established PTAAMG-Sig, in which ALDH2 is associated with a good patient prognosis." (PMID 39735553, 2024). "Herein, we revealed the expression features of the ALDH family between HCC and normal tissues through multi-omics bioinformatic analyses and validated the anti-tumor role of ALDH2." (PMID 38725845, 2024). "Both nanocomplexes demonstrated selective elevation of ROS (≥5 folds) and lipid peroxidation (≥2.5 folds) with lowering GSH level (>1.3 fold) and inhibiting ALDH2 activity (>36%) in tumor tissues (liver and lung)." (PMID 39076585, 2024). "We also observed differences in ALDH2 levels between tumor and normal tissues based on HPV status, anatomic subsite, and potential interactions between ALDH2 and ALDH6A1." (PMID 37476181, 2023). "The joint effects of ALDH2*2 and CYP2E1 (e.g., rs2031920) polymorphisms on tumor susceptibility in alcohol drinkers deserve to be evaluated." (PMID 36831600, 2023). "The trend persisted in subgroup analyses by anatomic tumor subsite and alcohol consumption status, despite the complexity of treatment strategies and treatment intent by ALDH2 levels." (PMID 37476181, 2023). "The results indicated that ACSL3, ADH1B, ALDH2, and HADHA had strongly associated with the tumor grade." (PMID 37540213, 2023). "When we stratified the population into different tumor subsites, the associations between ADH1B, ALDH2, and OPSCC became more and more evident." (PMID 37706329, 2023). "In vivo xenograft data indicated that overexpression of ALDH2 in NSCLC cells resulted in a significant increase in tumor growth." (PMID 35477569, 2022). "Western blot data indicated that the expression of ALDH2 was increased in NCI-H460/PTX tumor tissues when DZN was replaced by UNC0642." (PMID 35477569, 2022). "Acetaldehyde dehydrogenase 2 (ALDH2) not only is involved in aldehyde metabolism but also plays a key role in tumor growth." (PMID 36090994, 2022). "When DZN was replaced by the EHMT2 inhibitor UNC0642 to upregulate the expression of ALDH2, the tumor volume became bigger than in the other two groups." (PMID 35477569, 2022). "The SNPs of ADH1B rs1229984, ADH1C rs1789924, and ALDH2 rs671 were detected by Sanger sequencing using formalin-fixed paraffin-embedded tumor samples." (PMID 36212135, 2022). "Next, we used the NCI-H460/PTX xenograft tumor model to determine the anti-tumor effect of PTX when an epigenetic approach was used to rescue the expression of ALDH2." (PMID 35477569, 2022). "The findings highlight a crucial role played by ALDH2 to facilitate alcohol‐mediated tumor escape from immunity surveillance and promote tumor progression." (PMID 34026438, 2021). "ALDH2 protein expression was found to be remarkably higher in tumor tissues collected from mice after ethanol administration than those without ethanol treatment." (PMID 34026438, 2021). "Alcohol consumption was also found to induce ALDH2 expression in mice and tumor tissues of CRC patients." (PMID 34026438, 2021). "Intriguingly, ALDH2 and PD‐L1 protein expression are positively correlated in tumor tissues from the CRC patients." (PMID 34026438, 2021). "While BRIP1 represented the highest confidence hit predicted by PARIS, analysis of human tumor samples highlighted a consistent upregulation of FA genes in a low-ALDH2 expression background." (PMID 34454516, 2021). "ALDH2 has also been reported to regulate tumor proliferation by catabolizing some endogenous substrates derived from normal cell metabolism (e.g., 4-HNE)." (PMID 35096916, 2021). "A strong and positive correlation between ALDH2 and PD‐L1 protein expression was also observed from the tumor specimens from CRC patients." (PMID 34026438, 2021).
tumor (continued). "It is also noteworthy that the ALDH2 inhibition alone group exhibited increased TILs infiltration into the tumor tissues." (PMID 34026438, 2021). "In vivo experiments assessing subcutaneous tumor formation in mice showed that both tumor weight and tumor volume were greater in the PLVX-Flag H1299 mice than in the PLVX-Flag ALDH2 H1299 mice (p < 0.05)." (PMID 32850324, 2020). "Molecular biology experiments indicate that ALDH2 inhibits tumor progression largely by modulating the activity of the ALDH2-acetaldehyde-redox-AMPK axis." (PMID 33201835, 2020). "Both the mRNA and protein levels of ALDH2 were significantly lower in tumor tissues than in normal tissues and were lowest in BM tissues with increased migratory capacity." (PMID 32850324, 2020). "In terms of prognosis, a lower ALDH2 level was a poor prognosticator following primary resection, coincident with older age, embolus, larger tumor size, extrahepatic metastasis and microvascular invasion in HCC patients." (PMID 32140062, 2020). "The slow-metabolizing ADH1B*1/*1 genotype and the inactive heterozygous ALDH2*1/*2 genotype were significantly more common in the groups with neoplasia." (PMID 30629674, 2019). "A lower expression of ALDH2 in the tumor was observed, which was independent from the ALDH2 rs671 SNP variant and the expression of other mitochondria-associated protein coding genes." (PMID 29426835, 2018). "The cell-surface protein CD47, together with CD44 and ALDH2, that were found up regulated at gene level in the CSCs subset, were also overexpressed in a high fraction of tumor cells." (PMID 26452033, 2015). "Low ALDH2, high CCNE1 and SMAD3 were significantly associated with increase in tumor depth (T1, T2 and T3; P <0.05, chi-square test)." (PMID 25408144, 2014). "CCNE1 and SMAD3 were strongly stained in the tumor tissues but were weak in the normal tissues, whereas the ALDH2 staining showed the reverse pattern." (PMID 25408144, 2014). "Lastly, ALDH2 is found to be highly expressed by tumor cells compared to the stroma." (PMID 41550766, 2026). "In this regard, ALDH2 may suppress tumor growth by curbing AcAH-mediated oxidative stress and MAPK/ERK activation." (PMID 40558540, 2025). "Importantly, tumours in an in vivo xenograft model were sensitive to combined Nrf2 and ALDH2 inhibition." (PMID 40796730, 2025). "Meanwhile, we demonstrated that ALDH2 might serve as a new tumor marker and provide a basis for inhibiting PC progression." (PMID 40137171, 2025). "The subcutaneous tumour cells in the ALDH2-overexpression group were intact and compact." (PMID 40796730, 2025). "Considering that inhibition of Polθ is synthetically lethal in HR-deficient malignant cells, we speculated that inhibition of ADH5 and/or ALDH2 may enhance this anti-tumor effect." (PMID 40640557, 2025). "The therapies targeting modulation of ALDH2 activity or Trp metabolism could impact the tumor microenvironment and improve patient outcomes." (PMID 39132147, 2024). "Besides, we identified ALDH2 as a critical tumor suppressor in HCC development, and its low expression was associated with the activation of the β-Catenin/TGF-β1 signaling pathways." (PMID 38725845, 2024). "Low or high expression of ALDH2 promotes or inhibits tumor progression in various cancers." (PMID 38378847, 2024). "Moreover, ALDH2 was significantly reduced in tumor stage IV as compared to tumor stage I (P = 0.0172)." (PMID 38292172, 2024). "ALDH2 is related to immune cells in various tumor microenvironments." (PMID 38378847, 2024). "Moreover, multivariate COX regression results showed that ALDH2 can serve as an independent prognostic molecule and its transcriptional and translational levels were significantly reduced in the tumor tissues." (PMID 39132147, 2024).